HOXA5 (homeobox A5)
Diseases named in the same sentence as HOXA5 in open-access papers (continued):
Sharing a sentence is not in itself a finding about the gene and the disease.
tumor (continued). "However, examples of suppressive influences on tumor progression also exist, for example by HOXA5 in the maintenance of the epithelial phenotype, and HOXA4 in the inhibition of tumor cell migration [170*]." (PMID 31636382, 2020). "Analysis of HOX genes that are known to have oncogenic or tumor suppressive functions likewise reveals considerable variation, although Met-5A showed higher expression of the potential tumor suppressor genes HOXA4 and HOXA5 compared to the malignant cell lines." (PMID 26867567, 2016). "After 32 days, tumor weight in HoxA5 mice was reduced by ~50%, and correlated with a significant decrease in tumor vascular density as revealed by quantitative assessment of CD31+ vessels from tumors removed from control versus HoxA5-expressing mice." (PMID 25821967, 2015). "To date, in vivo analysis of the potential impact of HoxA5 on tumor angiogenesis has not been evaluated as HoxA5 null mice exhibit defective lung morphogenesis, and perturbed intestinal maturation resulting in perinatal mortality." (PMID 25821967, 2015). "When analyzing the frequency of detectable gene expression per tumor sample (presence/absence), no detectable expression of HOXA5 was observed in one case, while absence of amplification of either HOXD10 or HOXD11 transcripts was observed in two cases." (PMID 22227861, 2012). "Single-cell analysis revealed that HOXA5+ malignant cells enhance communication with fibroblasts and endothelial cells via IGFBP3-TMEM219 signaling, while HOXA5+ fibroblasts reshape the immune microenvironment via PTN-NCL, providing mechanistic insights into its tumor-promoting roles." (PMID 41209012, 2025). "This study for the first time highlights the tumor-suppressive role of LncRNA MAGI2-AS3 in HGSC and demonstrates its involvement in the regulation of miR-15b-5p, miR-374a-5p, and miR-374b-5p, and of their downstream mRNA targets (HOXA5, MTSS1, PTEN, and RECK) in HGSC cell lines." (PMID 31842477, 2019).
cancer (74 papers, 2012 to 2025). A tumor composed of atypical neoplastic, often pleomorphic cells that invade other tissues. "eQTL-GWAS colocalization linked rs3757640 to cancer risk, supporting genetic-epigenetic interplay in HOXA5 regulation." (PMID 41209012, 2025). "eQTL-GWAS colocalization indicated that rs3757640 (HOXA5) shares genetic variation with cancer risk, providing very strong evidence for colocalization under the specified model (PP.H4.abf = 1)." (PMID 41209012, 2025). "HOXA5 affects apoptosis, differentiation, and cell proliferation in cancer, whereas HOXB9 expression is associated with immune response and prognosis in a variety of cancers." (PMID 40305321, 2025). "HOXA5, which encoded a DNA-binding transcription factor, can control gene expression, cell morphogenesis, and differentiation in various cancer cells." (PMID 34988109, 2021). "Beyond this, an emerging group of studies shows the dysregulation of HOXA5 in various solid/adult/pediatric/cancers or hematological malignancies and linked with higher pathological grade and poorer disease outcome." (PMID 33384715, 2020). "And Hoxa5 is known to be associated with the process of cell proliferation, migration and apoptosis in cancer cells." (PMID 29221131, 2017). "Hypermethylation of HOXA5 has been reported in several cancer types and is associated with decreased expression." (PMID 24674026, 2014). "cBioPortal analysis revealed HOXA5 mutation sites across cancers." (PMID 41209012, 2025). "HOXA5, a developmental transcription factor, has been linked to prognosis in various cancers, but its role in EC remains unclear." (PMID 40805172, 2025). "Aberrant HOXA5 expression has been associated with various cancers." (PMID 37834206, 2023). "These include STAT3 and HoxA5, which have been associated with cancer induction." (PMID 31040909, 2019). "Additionally, dysregulated HOXA5 expression has been observed in several types of cancers and is associated with their progression." (PMID 31159758, 2019). "HOXA5 is associated with various cancers; however, its association with EC remains unclear." (PMID 37834206, 2023). "In prostate cancer, HOXA5 has been shown to suppress cancer cells’ stemness and malignancy by regulating the SPRY2/MEK/ERK pathway." (PMID 40805172, 2025). "To address these gaps, we conducted a comprehensive multi-omics analysis of HOXA5 across 33 cancer types." (PMID 41209012, 2025). "HOXA5 was significantly dysregulated across cancers, with elevated expression in AML and GBM, and reduced expression in BRCA and LUAD." (PMID 41209012, 2025). "Pan-cancer transcriptome analysis indicated significantly high HOXA5 expression in GBM and LAML, but low expression in BRCA and LUAD." (PMID 41209012, 2025). "HOXA5 (homeobox A5) exhibits context-dependent roles in cancer, but its pan-cancer spatial immune regulatory functions and therapeutic potential remain poorly understood." (PMID 41209012, 2025). "Crucially, we uncovered HOXA5’s oncogenic potential at a pan-cancer scale—its elevated expression in GBM and AML promotes malignancy." (PMID 41209012, 2025). "This pan-cancer study systematically characterized HOXA5’s expression patterns, immune interactions, clinical significance, and mechanistic role in AML using multi-omics and functional validation." (PMID 41209012, 2025). "This divergence emphasizes the tissue-specific regulatory networks orchestrated by HOXA5 and solidifies its characterization as a dual-function regulator in cancer biology." (PMID 41209012, 2025).
cancer (continued). "Specifically, cancer stem cell markers LGR5, CD44v6, and AC133 drastically decreased with HOXA5 re-expression in vitro, indicating that loss of HOXA5 is imperative to stem cell transformation." (PMID 39858044, 2025). "Nonetheless, the biological function of HOXA5 in cancer still remains controversial and varies among different organ types." (PMID 37845209, 2023). "The results showed that the expression level of HOXA5 was significantly higher in cancer tissues than in normal tissues." (PMID 37834206, 2023). "For instance, alterations in the HOX family members HOXA5 and HOXD10 have been implicated in the development and progression of cancer." (PMID 37812190, 2023). "Increasing evidence has shown the involvement of HOXA5 in cancer cell proliferation, metastasis, and other processes." (PMID 37845209, 2023). "The downregulation of HOXA5 increased the expression of HOXB6 and HOXB7, which were associated with poor clinical outcomes in cancer patients." (PMID 35054365, 2022). "Another cancer stemness promoting gene, HOXA5, was also found to be regulated by H3K27me3 in the tamoxifen resistant MCF7 cell line." (PMID 35330189, 2022). "Compared with HOXA5, the better discrimination of normal and cancer tissues by ADHFE1 signifies the great potential for this gene as a methylation marker to indicate pathological changes." (PMID 35054365, 2022). "Further experiments found a positive correlation between the expression of linc00312 and the transcription factor HOXA5 which was a tumor-suppressor involved in several cancers progression." (PMID 35963868, 2022). "The differential expression of HOXA4 and HOXA5 in LUAD also showed preferable ability of discriminating LUAD from non-cancer lung samples." (PMID 35370463, 2022). "There have been literature documents of the involvements of HOXA4 and HOXA5 in formation and progression of various human cancers through active or inhibitory roles in proliferation, growth, migration and apoptosis in cancer cells 37-42." (PMID 35370463, 2022). "Among 47 studies, 11 studies reported up-regulated HOXA5 mRNA transcripts and 36 with down-regulated HOXA5 mRNA transcripts in cancer tissues, related to the controls." (PMID 36167790, 2022). "HOXA5 is a tumor suppressor gene dysregulated in expression and methylation in several types of cancer." (PMID 35361921, 2022). "Retinoic acid is known to stimulate the expression of HOXA5 in some cancer cells and has been evaluated as a preventive and therapeutic agent." (PMID 33414417, 2021). "Retinoic acid has been used as a therapeutic agent for a variety of cancers and HOXA5 is a critical mediator of this effect." (PMID 33414417, 2021). "Our study is the first to provide evidence that HOXA5 is not only involved in tumorigenesis and/or cancer progression but is also a molecular marker for tamoxifen resistance." (PMID 34149926, 2021). "The role of HOXA5 in promoting or suppressing cancer in malignant tumors from different tissues has been gradually clarified." (PMID 34027794, 2021). "Hypermethylation of HOXA5 has been reported in several cancer types, and in these cancers it shows reduced expression." (PMID 32736574, 2020). "A previous study reported a statistically significant downregulation of HOXA5 expression in carcinoma relative to normal colon tissue." (PMID 31165042, 2019). "Homeobox A5(Hoxa5), a member of the Hox family, plays a important role in the regulation of proliferation and apoptosis in cancer cells." (PMID 29221131, 2017). "Further studies demonstrated that HOXA5 was universally diminished in cancerous tissues and promoted malignant progression by affecting cancer cell proliferation, apoptosis and metastasis." (PMID 28423732, 2017).
cancer (continued). "We found that ectopic expression of HOXA5 in highly invasive cancer cells suppressed cell migration, invasion, and filopodia formation in vitro and inhibited metastatic potential in vivo." (PMID 25875824, 2015). "This inverse relationship in AML diverges from the positive associations between HOXA5 and these pathways observed in the pan-cancer analysis of solid tumors, highlighting a fundamental difference in HOXA5’s mechanistic role between solid and hematological malignancies." (PMID 41209012, 2025). "Our findings suggest that HOXA5 may act like a double-edged sword—encouraging cancer cell growth while limiting their ability to spread." (PMID 40805172, 2025). "Indeed, abnormal HOXA5 promoter methylation is the most common way by which HOXA5 is dysregulated in developmental diseases and several cancers." (PMID 37626900, 2023). "Consistently, in vivo assays further indicated that the expression of stemness markers was significantly increased following HOXA5 knockdown, suggesting that HOXA5 inhibition could attenuate the cancer stemness of PCa cells." (PMID 37845209, 2023). "While HOXA5 is a transcriptional factor promoting cancer cell proliferation, this research indicated that linc00312 may play an important role in cell proliferation and tissue invasion." (PMID 35963868, 2022). "Based on the knowledge that epigenetic marks, especially methylation, change with age we aimed to identify genes with significant age-related methylation differences which led to the detection of HOXA5 as a potential cancer-related candidate marker for old age." (PMID 33547267, 2021). "Three dmCGs with MD > 20% were identified which were associated with HOXA5, further RYR1, known to code for a ryanodine receptor in skeletal muscles and DUSP3, which is implicated in cancer and negatively regulates members of the mitogen-activated protein (MAP) kinase superfamily." (PMID 33547267, 2021). "To date, there have been contradictory observations on the role of HOXA5 in cancer." (PMID 34149926, 2021). "Hence, we examined the mRNA expression level of HOXA5 in 22 cancer-free individuals (IM = 11, normal = 11)." (PMID 32736574, 2020). "Previous studies have revealed dysregulated HOXA5 expression in several cancers." (PMID 31159758, 2019). "In the present study, we found that ectopic HOXA5 could inhibit cancer cell migration and invasion, both in vitro and in vivo, which is consistent with previous reports." (PMID 28423732, 2017). "However, recent studies about Hoxa5 mainly focus on cancer cells and the precise molecular mechanisms involved in the regulation of Hoxa5 on adipocyte apoptosis are unclear." (PMID 29221131, 2017). "Not surprisingly, changes in the epigenetic control of Hoxa5 have profound effects on its expression that are often linked to cancer." (PMID 29615582, 2016). "Interestingly, patients with high HOXA5 levels had lower amounts of markers related to blood vessel formation and tissue invasion, which may slow down cancer’s spread." (PMID 40805172, 2025). "Moreover, the loss of HOXA5 could promote PCa malignancy, EMT phenotype and drive cancer stemness through a previously-unreported TRAF7/HOXA5/SPRY2–MEK/ERK signaling axis." (PMID 37845209, 2023). "Thus, HOXA5 has the potential to inhibit cancer stem cell proliferation and metastasis." (PMID 34617205, 2022). "Therefore, aberrant HOXA5 expression can lead to various diseases, including cancer." (PMID 26219418, 2015).
cancer (continued). "Likewise, level of HOXA5 protein varies depending on the cancer type." (PMID 26219418, 2015). "HOXA5 has been known principally for its role in pattern formation during development; however, several studies have suggested that it may also play a role in cancer cell migration, invasion and metastasis." (PMID 25875824, 2015). "Additionally, induction of HOXA5 is important for retinoic acid (RA)-mediated apoptosis and cellular growth inhibition acting directly downstream of RARβ, and plays an important role in RA-mediated anti-cancer activity." (PMID 22876840, 2012). "Homeobox protein Hox-A5 (HOXA5) regulates proliferation, differentiation, invasion, apoptosis, cancer stem cell progression, and the immune microenvironment." (PMID 41440381, 2025). "We integrated multi-omics data from 33 cancer types (TCGA, n=11,096; GTEx, n=7,469; TISCH2; spatial transcriptomics) to characterize HOXA5 expression, genomic alterations, and immune interactions." (PMID 41209012, 2025). "In BC, CAFs-derived sEVs containing miR-181d-5p promote cancer cell proliferation, invasion, migration and EMT while inhibiting apoptosis by targeting caudal-related homeobox 2 (CDX2) and its downstream gene-homeobox A5 (HOXA5)." (PMID 36499561, 2022). "A significant reduction of spheroids in HOXA5 knockdown TAMR cells compared to control cells was observed, supporting the role of HOXA5 involvement in cancer stemness." (PMID 34149926, 2021). "We found that the methylation percentages of HOXA5, HOXA2, and HOXA6 in CRC tissue were up to 67.62, 58.36, and 31.32%, respectively, and ranked first in CRC among all cancer types analyzed." (PMID 31165042, 2019). "Transwell assay demonstrated that up-regulated HOXA5 in A549 and SPC-A1 prevented cancer cells from migration and invasion." (PMID 28423732, 2017). "Notably, we observed that HOXA5 exhibited positive correlations with angiogenesis, EMT, and stemness in our pan-cancer analysis—likely driven by its role in solid tumors—yet showed a negative association with angiogenesis and metastasis pathways in AML." (PMID 41209012, 2025). "The transcription factor HOXA5, from the HOX gene family, has long been studied due to its critical role in physiological activities in normal cells, such as organ development and body patterning, and pathological activities in cancer cells." (PMID 37626900, 2023). "Previously, miR-196a was proven to enhance cancer cell proliferation by targeting FOXO1 and HOXA5." (PMID 38067033, 2023). "HOXA5, which is identified as a novel target of TRAF7, has been demonstrated to bind directly to the SPRY2 promoter and subsequently regulate the MEK/ERK signaling pathway, thus to affect PCa proliferation, metastasis, and cancer stemness." (PMID 37845209, 2023). "Endocrine system development and cancer growth-related ceRNA regulation are found in TNBC; HOXA5, SCAPER, PAK6, PBX1, PITX1, and ALOX15B are the relevant genes involved; and hsa-miR-296-5p, hsa-miR-185-5p, hsa-miR-7851-3p, hsa-miR-3187-3p, and hsa-miR-10396b-5p are the relevant miRNAs involved." (PMID 37483500, 2023). "Also, 9-cis-retinoic acid suppressed cancer cells in CRC by increasing apoptosis and inhibiting COX-2 through the activation of PPARγ, while retinal suppressed CRC by inducing HOXA5 and repressing stem cell markers prominin 1 and ALDH1." (PMID 35178443, 2022). "The DNA methylation profiles of the 3 HOXA gene promoter regions were downloaded from TCGA, and the results demonstrated that the methylation levels of HOXA5, HOXA2, and HOXA6 were significantly elevated in cancer tissues compared with normal tissues (p < 0.0001)." (PMID 31165042, 2019). "In our article, we found that HOXA5 and HOXA6 were more likely to be methylated in patients < 60 years of age, so these two genes may serve as screening indexes for younger cancer patients." (PMID 31165042, 2019).
cancer (continued). "The constructed TF and miRNA regulatory networks showed that hub nodes including miR-126-3p, miR-30c-2-3p, HOXA5, MEIS1 and TBX5 were markedly different in two separate TF and miRNA enrichment analyses, and their levels were significantly decreased in cancer tissues." (PMID 26035298, 2015). "Unlike other tumors, the cancer-promoting function of HOXA5 in lung cancer needs further study." (PMID 35963868, 2022).
cardiovascular disease (4 papers, 2022 to 2024). "Recent epigenome-wide methylation analysis has revealed that DNA methylation-dependent HOXA5 repression could contribute to pathologic tissue remodeling seen in CKD-related cardiovascular disease." (PMID 34973136, 2023).